GAST (gastrin)
Diseases named in the same sentence as GAST in open-access papers (continued):
Sharing a sentence is not in itself a finding about the gene and the disease.
gastrinoma (continued). "Gastrinomas are neuroendocrine tumors that are characterized by hypersecretion of gastrin, resulting in Zollinger Ellison syndrome (ZES), of which nearly 80% are sporadic and the other 20-25% are associated with multiple endocrine neoplasia syndrome (MEN) type 1." (PMID 40291307, 2025). "Gastrinomas are rare functional neuroendocrine tumors, most commonly arising in the pancreas or duodenum, and are typically associated with Zollinger–Ellison syndrome (ZES), a clinical condition resulting from excessive secretion of gastrin." (PMID 40647278, 2025). "Gastrin is a trophic peptide that promotes gastrointestinal cell proliferation, suggesting that loss of menin may contribute to the initiation and progression of gastrinomas through increased gastrin expression." (PMID 39336822, 2024). "However, in patients with gastrinomas, the gastrin levels paradoxically continue to rise or remain elevated after secretin administration, with levels more than 120 pg/mL being diagnostic of ZES." (PMID 38672582, 2024). "The measurement of gastrin levels plays a pivotal role in diagnosing gastrinomas and ZES." (PMID 38928704, 2024). "Consistent with its ability to repress gastrin gene expression, a heterozygous MEN1 variant and two heterozygous mutations were identified in all patients diagnosed with duodenal and pancreatic gastrinomas in our previously published cohort." (PMID 37492626, 2023). "Interestingly, signet ring cell carcinomas have been described in patients with multiple endocrine neoplasia type I (MEN1) with gastrinoma, indicating an important role of gastrin in the pathogenesis." (PMID 37686307, 2023). "Her gastrin level was high enough to suspect gastrinoma (1341 pg/mL; standard range, 42–200 pg/mL)." (PMID 36110332, 2022). "Patients with MEN1 are at a higher risk of developing Zollinger-Ellison syndrome (ZES) due to the growth of neuroendocrine tumors called gastrinomas that release gastrin leading to hypersecretion of acid in the stomach resulting in severe ulcerative disease of the upper GI tract." (PMID 35919366, 2022). "Fasting gastrin levels and secretin stimulation tests can be used in the diagnosis of gastrinomas." (PMID 36291833, 2022). "Our research may suggest a possible therapeutic use of PD‐1/PD‐L1 inhibition in Zollinger Ellison syndrome patients with either primary gastrinomas or other gastrin‐producing tumors." (PMID 35899973, 2022). "We initially examined fasting serum gastrin concentrations in patients who had no known risk factors for hypergastrinaemia (gastrinoma, PPI use, H. pylori infection or atrophic gastritis)." (PMID 34867785, 2021). "Interpretation of fasting serum gastrin concentrations therefore needs to take into account the complete clinical picture and it is not possible to set a cut-off value to identify patients who require further investigation for a gastrinoma." (PMID 34867785, 2021). "A secretin stimulation test can be performed, if a gastrinoma is suspected but gastric pH and serum gastrin levels are not diagnostic." (PMID 34671320, 2021). "Gastrin level was elevated (100 times upper limited normal) in 1 case (unknown primary) which clinically was in keeping with metastatic gastrinoma." (PMID 34504148, 2021). "However, in MEN-1 patients, type-2 carcinoids also regress after excision of all gastrinomas and serum gastrin has returned to normal." (PMID 31963924, 2020). "Screening for gastrinoma is performed through annual evaluation of gastrin (± gastric pH)." (PMID 31263451, 2019). "There are a number of reasons that ZES is an excellent model to study the effects of chronic, lifelong hypergastrinemia in man, with >99% of patients have fasting hypergastrinemia due to the ectopic secretion of gastrin from a neuroendocrine tumor (gastrinoma)." (PMID 31623145, 2019). "This occurs via the release of gastrin by neuroendocrine tumors known as gastrinomas." (PMID 28321346, 2017).
gastrinoma (continued). "Gastrinomas with large size (>20 mm) and high gastrin secretion are reported to be aggressive." (PMID 28270118, 2017). "Thus, at the time of the second SASI test, secretion of gastrin into the blood from a hepatic gastrinoma was suppressed by one-hundredth, and on the other hand, antral G cells were actively secreting gastrin into the blood." (PMID 29181825, 2017). "It is also important to determine gastrin levels in cases of suspected gastrinoma." (PMID 28194228, 2017). "Gastrinomas, one of the common functional neuroendocrine tumors, can over-synthesize gastrin and are usually presented as recurrent peptic ulcer disease, gastroesophageal reflux disease, diarrhea, or abdominal pain and are referred to as Zollinger-Ellison syndrome (ZES)." (PMID 26077245, 2015). "Appropriate gastrin secretion occurs with neutral pH, while unopposed gastrin secretion in the presence of an already acidic pH is an inappropriate response, as in gastrin-producing tumors or gastrinomas." (PMID 25698559, 2015). "Histologic preparations should be reevaluated by IHC to guide the search for the primary tumor: TTF-1 (pulmonary or medullary thyroid carcinoma), CDX-2 (intestinal), PAX-8, histidine-decarboxylase (pancreatic), xenin (duodenal), gastrin (occult gastrinoma), and PP/glucagon (pancreatic)." (PMID 25038902, 2014). "If gastrin is 100–1000 ng/mL and pH < 2, then gastrinoma is possible in the right clinical context." (PMID 23316222, 2012). "The diagnosis of gastrinoma is based on the finding of levels of gastrin superior than 100 pg/dL." (PMID 24213321, 2012). "Intraoperative selective intra-arterial secretin stimulation and venous sampling of gastrin may be helpful in localising small sporadic gastrinomas." (PMID 24213225, 2012). "Elevated serum gastrin levels confirmed the gastrinoma diagnosis." (PMID 23487241, 2011). "The fact that our patients suffer from ZES and related gastrinomas, and the trend in our data, however, suggests that an excess production of gastrin may be one component in the production of hypertrophic GOH." (PMID 19587828, 2009). "Therefore, a calcium injection into vascular territories not involving gastrinomas does not cause a rise in the serum gastrin level." (PMID 33206240, 2020). "At the time of the second SASI test, the hepatic gastrinoma experienced suppressed production of gastrin granules due to the administration of octreotide acetate, so the serum IRG levels at the second SASI test might have been lowered by about 1% compared to those at the first SASI test." (PMID 29181825, 2017). "Additionally, menin may suppress gastrinoma development by repressing gastrin expression." (PMID 39336822, 2024). "Gastrinoma cells were strongly stained for SPY, suggesting active SV involved in possible autonomous gastrin secretion through endocytosis." (PMID 32020844, 2020). "Type-2 gastric carcinoids occur in the presence of gastrinoma, primarily in those with MEN-1/ZES, rarely in uncomplicated sporadic ZES, comprise 5%–6% of gastric carcinoids, are gastrin-dependent, and malignant in 10%–30% of cases." (PMID 31963924, 2020). "The other functioning Pan-NETs including gastrinomas and glucagonomas are also more strongly positive for SPY than CgA, suggesting active SV involvement on the early gastrin and glucagon section, respectively." (PMID 32020844, 2020). "Gastrin determination has a key role in the evaluation of patients with signs and symptoms suggestive of Zollinger–Ellison syndrome (ZES, see “Box 3, Gastrinoma”)." (PMID 25038902, 2014). "An elevated serum Gastrin concentration can be used as a sensitive indicator of gastrinoma but is not usually specific." (PMID 40291307, 2025). "The process of tumour detection involved biochemical screening tests including gastrin, glucose, insulin, chromogranin-A, pancreatic polypeptide, glucagon, vasointestinal polypeptide, prolactin and IGF-1 to assess for gastrinoma, insulinoma, enteropancreatic and anterior pituitary tumours." (PMID 31797261, 2020).
gastrinoma (continued). "In this study, each Pan-NET was first diagnosed for the presence of the specific hormone by immunostaining of four pancreatic hormones and gastrin, with which diagnosis of insulinoma, glucagonoma, PPoma, gastrinoma, and non-functioning tumor was rendered." (PMID 32020844, 2020). "Secondarily, the duodenum was carefully examined using the anti-gastrin antibody staining and a holoblastic cleavage method, but we found no gastrinoma cells only hyperplastic Brunner’s glands." (PMID 29181825, 2017). "Thirdly, the patient’s postoperative serum gastrin levels have remained within the normal range for about 4 years, and there has been no recurrence of gastrinomas or Zollinger-Ellison syndrome." (PMID 29181825, 2017). "Similar to previous studies, we found that CgA levels in patients with gastrinomas were much higher than those in patients without gastrin-secreting PNETs." (PMID 25099181, 2014). "In our case, the absence of symptoms of classical gastrinoma and the persistence of extremely elevated gastrin after radical tumor excision rule out the diagnosis of Zollinger–Ellison syndrome." (PMID 23432909, 2013). "Neither had pre-operative serum gastrin levels and only one of the two cases reported a clinical syndrome consistent with a functional gastrinoma." (PMID 24213231, 2012). "Considering that patients with MEN1 may have gastrinoma, gastrin levels were measured and found to be 27.30 pg/mL (normal range:13.0-115.0 pg/mL), so a diagnosis of gastrinoma was not supported." (PMID 40421248, 2025). "Thirty-five pancreatic neuroendocrine tumors (Pan-NETs) were studied, consisting of 14 insulinomas, 8 gastrinomas, 2 glucagonomas, 6 pancreatic polypeptidomas and 5 non-functioning tumors, and were immunostained for four pancreatic hormones, gastrin, CgA, and SPY." (PMID 32020844, 2020). "After admission, the diagnosis of gastrinomas was presumed even without gastrin examination." (PMID 33204258, 2020). "Indeed, while PPI treatment is very efficient to downregulate gastrin hypersecretion, MEN1 related gastrinomas are usually multiple and located in the duodenum, hence, it is unlikely to achieve curative resection using conservative pancreatic surgery (such as enucleation]." (PMID 32947997, 2020). "Compared with those of non-gastric origin, patients with gastric gastrinomas had significantly elder age (56.3 ± 11.2 vs. 39.7 ± 17.4, p = 0.024) and higher gastrin level (512.3 ± 323.3 vs. 207.7 ± 234.7 mg/ml, p = 0.030), however, smaller tumor size (7.3 mm vs. 5.1 mm, P = 0.065)." (PMID 26077245, 2015). "Acquired immune deficiency syndrome (HIV enteropathy), carcinoid syndrome and gastrinoma can also be excluded due to negative HIV serology, normal levels of 5‐HIAA in 24‐h urine and normal serum gastrin, respectively." (PMID 33398457, 2021). "However, serum gastrin levels in these dogs did not exceed 3 times the upper reference limit (URL), excluding the diagnosis of gastrinoma." (PMID 38672316, 2024).
atrophic gastritis (75 papers, 2003 to 2026). "The clinical significance of long‐term hypergastrinemia caused by acid blockers is still unclear, and serum gastrin level can be influenced by multiple factors including gastric atrophy, chronic kidney disease, glucocorticoid therapy, as well as VPZ/PPI use." (PMID 38919514, 2025). "Elevated gastrin, especially with severe atrophic gastritis, suggests a higher risk of metachronous cancer, but EGD remains essential." (PMID 39518740, 2024). "A systematic review evaluated the diagnostic accuracy of combining pepsinogen, gastrin-17 and anti-Hp antibody serum tests for diagnosing atrophic gastritis." (PMID 38999928, 2024). "Another biomarker associated with atrophic gastritis is gastrin-17 (G-17), which is secreted by G endocrine cells and depends on gastric acidity." (PMID 36767516, 2023). "Association of gastric atrophy or cancer with levels of serum pepsinogens, gastrin-17 and anti-Helicobacter pylori IgG antibody have been extensively studied." (PMID 36051244, 2022). "Foveolar epithelial cell proliferation within the gastric pit coincides with a marked loss of parietal cells and reduced acid secretion (gastric atrophy), further potentiating gastrin gene expression." (PMID 35330921, 2022). "PPI use, H. pylori infection and atrophic gastritis all caused significant elevations of median fasting gastrin concentrations." (PMID 34867785, 2021). "Th1 cytokines like IL-6 promote chronic atrophic gastritis and predisposition to tumorigenesis through inhibition of gastrin and somatostatin." (PMID 32231118, 2020). "So far, it has been demonstrated that serum pepsinogens (PGs), and gastrin 17 (G17) are useful for screening individuals at elevated risk to develop atrophic gastritis but they are suboptimal biomarkers to screen individuals for GC." (PMID 29518896, 2018). "Taken together, it is possible that gastric atrophy results in a reduced gastric acidity and a higher gastrin secretion, which expand β-cell mass and lower the risk of incident diabetes." (PMID 28045079, 2017). "Corpus gastritis is associated with the loss of parietal cells, low acid secretion, high gastrin production and gastric atrophy (multifocal atrophic gastritis)." (PMID 28103315, 2017). "Negativity for anti-Hp associated with positivity for PCA, IFA and raised gastrin in patients with anemia increases the positive predictive value for the diagnosis of gastric atrophy." (PMID 23251219, 2012). "Serum gastrin levels are generally elevated in patients with gastrin‐producing tumors (neuroendocrine tumors), severe gastric atrophy due to autoimmune gastritis (AIG) or H. pylori‐associated gastritis, and in those receiving potent acid suppressive therapy such as proton pump inhibitors." (PMID 40995608, 2025). "could stimulate gastrin and IL-8 cytokine production, which suggests they can cause gastritis or participate in the transformation towards atrophic gastritis." (PMID 34645495, 2021). "High gastrin levels may help to explain the association between several conditions and osteoporosis, such as pernicious anemia, the use of proton pump inhibitors, and atrophic gastritis." (PMID 41206736, 2026). "While the serum gastrin level is proportionate to the degree of gastric atrophy, the precise mechanism of the development of a cobblestone‐like mucosal change is unclear." (PMID 38919514, 2025). "For these mucosal lesions, we have evaluated the association with the type of acid blockade, patient gender, Helicobacter pylori infection status, the degree of gastric atrophy, and serum gastrin levels." (PMID 38919514, 2025). "Eight out of nine gastric NETs were classified as type 1, with either elevated gastrin levels or a history of atrophic gastritis supported by EGD findings." (PMID 40217599, 2025).
atrophic gastritis (continued). "This hypergastrinemia mimics the elevated serum gastrin levels observed in humans with chronic atrophic gastritis and achlorhydria, which is thought to promote epithelial proliferation and potentially contribute to carcinogenesis." (PMID 40673273, 2025). "It is well known that pepsinogen (PG) and gastrin (GAS) can be used as serological indexes in the diagnosis of chronic atrophic gastritis." (PMID 39834822, 2024). "GastroPanel is a non-invasive tool for the diagnosis of atrophic gastritis; it combines serological assays of PG, gastrin, and anti-Hp Abs." (PMID 37210509, 2023). "This normal concentration of gastrin was then used to distinguish patients with atrophic gastritis from true A in the endoscopically-evaluated group." (PMID 37210509, 2023). "That study subsequently reported that the sensitivity, specificity and area under curve of gastrin-17 were less than the PGI, PGII and PGI/II ratio, suggesting inferior clinical value of gastrin-17 in screening chronic atrophic gastritis than that of PG." (PMID 35066729, 2023). "Their study demonstrated a lower statistical power of gastrin-17 than the PGI, PGII, and PGI/II ratio, suggesting a higher clinical value of PG in screening chronic atrophic gastritis than gastrin-17." (PMID 38069253, 2023). "There are many reports on the PG method and anti-Hp Abs in Japan; however, there are few reports on gastrin as a screening method for atrophic gastritis, thus making our study valuable." (PMID 37210509, 2023). "This suggested that H. pylori-positive subjects with higher UBT values were less likely to have pepsinogen-I ≤70 ng/mL (a serum marker for gastric atrophy), but more likely to have gastrin-17 >5.70 pmol/L (a marker for peptic ulcer)." (PMID 36051244, 2022). "INS-GAS (insulin-gastrin) transgenic mice with high levels of circulating gastrin develop spontaneous atrophic gastritis and GIN with an 80 % prevalence 6 months after H. pylori infection." (PMID 34556055, 2021). "Due to the use of both atrophic gastritis biomarkers, the panel test appears to have a higher sensitivity and specificity than serum pepsinogens and gastrin-17 tests alone." (PMID 34136433, 2021). "In total, 2,847 people aged > 40 years old underwent serological noninvasive screening for atrophic gastritis by identifying postprandial gastrin-17 and pepsinogen-1 in the fasting state." (PMID 32102507, 2020). "Nonetheless, it is possible that an elevated level of serum gastrin, perhaps due to the intake of acid-suppressing drugs, delays the recovery of gastric atrophy." (PMID 31003453, 2019). "Two-thirds of the H. pylori-positive women had non-atrophic gastritis, based on elevated serum gastrin, but normal PG-I." (PMID 31810343, 2019). "As a result of increase of serum concentration of gastrin accompanying with increased grades of atrophic gastritis, the serum gastrin level is taken as a significant biomarker for evaluating the status of gastric inflammation." (PMID 30382864, 2018). "And that patients with autoimmune atrophic gastritis showed similarities to individuals with H. pylori-induced atrophic gastritis by predicted pathway analysis, despite markedly different serum gastrin concentrations." (PMID 29095917, 2017). "PPI treatment did not significantly alter the gastric microbiota from that of a normal stomach, despite serum gastrin concentrations being comparable to those found in patients with H. pylori-induced atrophic gastritis." (PMID 29095917, 2017). "With the progression of the severity of gastric atrophy, there is a progressive reduction in gastric acidity and a progressive increase in luminal gastrin concentrations." (PMID 28045079, 2017). "Atrophic gastritis, which often results in increased gastrin levels, is characterized by elevated CgA plasma levels." (PMID 29232390, 2017). "Serum gastrin is usually markedly increased as a result of gastric atrophy and the increase of pH value." (PMID 28057043, 2017).